RN7SL667P (RNA, 7SL, cytoplasmic 667, pseudogene)
Gene: Miscellaneous RNA gene on chromosome X (153,403,844 to 153,404,141, reverse strand). Ensembl gene ENSG00000265170.
Homologues: Orthologues: macaque Metazoa_SRP (39% identical), macaque Metazoa_SRP (38% identical), macaque Metazoa_SRP (37% identical), macaque Metazoa_SRP (36% identical), macaque Metazoa_SRP (35% identical). Paralogues in human: RN7SL134P (76% identical), RN7SL784P (76% identical), RN7SL811P (75% identical), RN7SL774P (74% identical), RN7SL96P (73% identical), RN7SL154P (73% identical), Metazoa_SRP (73% identical), RN7SL123P (73% identical), RN7SL474P (73% identical), Metazoa_SRP (71% identical), RN7SL596P (71% identical), RN7SL693P (71% identical), and 707 more.